ACBD3 (acyl-CoA binding domain containing 3)
Diseases named in the same sentence as ACBD3 in open-access papers (continued):
Sharing a sentence is not in itself a finding about the gene and the disease.
breast tumor (1 paper, 2022). "Distant metastasis-free survival (DMFS) was less likely when ACBD3 expression was high: the upper quartile DMFS was 138 months for the cohort as a whole when ACBD3 was expressed below the median level in breast tumor and 68 months when ACBD3 was expressed above the median." (PMID 36012147, 2022).
diabetes (1 paper, 2012). "More studies are warranted to clarify ACBD3's biological roles in maintaining lipid homeostasis and therapeutic potentials for diseases attributed to imbalanced lipid metabolism such as obesity, diabetes, cancer and neurodegeneration." (PMID 23166793, 2012).
enterovirus infection (1 paper, 2025). "During enterovirus infection, ACBD3 recruits PI4KB to RNA replication sites to promote the synthesis of the phosphatidylinositol-4-phosphate (PI4P) lipids that are critical for the enteroviral RNA polymerase." (PMID 40207930, 2025). "Interestingly, we show that despite ACBD3’s well-characterized role in enterovirus infection, it promotes flavivirus infection with a different mechanism not related to PI4KB recruitment and PI4P synthesis." (PMID 40207930, 2025).
Flavivirus Infections (1 paper, 2025). Infections with viruses of the genus FLAVIVIRUS, family FLAVIVIRIDAE. "Together, this suggests that ACBD3 facilitates flavivirus infection by bringing the NS4B and TERM-Golgi contact sites in close contact, either by direct or by indirect interactions." (PMID 40207930, 2025). "ACBD3 remodels ERES-Golgi contacts to mediate Golgi transport of the STING receptor during bacterial infection, suggesting that it is involved in the process during flavivirus infection as well." (PMID 40207930, 2025). "However, at 1.25 μM, the compound did not inhibit LGTV or TBEV replication in A549 cells, showing that PI4KB recruitment is not the proviral mechanism for ACBD3 in flavivirus infection." (PMID 40207930, 2025). "Interestingly, productive infection was also restored by complementation with the FQ mutant that has a non-functional PI4KB binding site, further confirming that ACBD3 does not promote flavivirus infection via PI4KB recruitment." (PMID 40207930, 2025).
Hepatic steatosis (1 paper, 2017). Steatosis is a term used to denote lipid accumulation within hepatocytes. "In consistent with their facilitatory role in lipid degradation, circRNA_0046367-induced normalization of both CPT2 and ACBD3 resultantly attenuated the hepatic steatosis by statistical downregulation of TG content." (PMID 29018509, 2017).
ovarian carcinoma (1 paper, 2025). A malignant neoplasm originating from the surface ovarian epithelium. "In the highly metastatic ovarian cancer cell line TOV21-G, which harbors a heterogeneous R190fs* mutation, ectopic expression of ACBD3 suppressed both cell migration and invasion." (PMID 40189704, 2025).
paraganglioma (1 paper, 2023). A benign or malignant neoplasm arising from paraganglia located along the sympathetic or parasympathetic nerves. "Among the molecular subtypes of Kinasesignaling in pheochromocytoma & paraganglioma (PCPG), ACBD3 showed the highest expression." (PMID 38098097, 2023).
Salmonella Infections (1 paper, 2016). Infections with bacteria of the genus SALMONELLA. "As an alternative test of the relevance of the SseG-ACBD3 interaction during Salmonella infection, we attempted to obtain a point mutant of SseG that fails to interact with ACBD3 in yeast." (PMID 27406559, 2016).
sarcoma (1 paper, 2023). A usually aggressive malignant neoplasm of the soft tissue or bone. "Because of the difficulty of integrating all sarcoma-related data, we verified the remaining three results using the GEO database and found that only the prognosis of GBMLGG was correlated with ACBD3 expression." (PMID 38098097, 2023).
skin cutaneous melanoma (1 paper, 2023). "The CCLE database revealed that ACBD3 was highly expressed in skin cutaneous melanoma (SKCM), BRCA, GBM, KIRC, brain lower grade glioma (LGG), and THCA." (PMID 38098097, 2023).
triple-negative breast carcinoma (1 paper, 2022). An invasive breast carcinoma which is negative for expression of estrogen receptor (ER), progesterone receptor (PR), and human epidermal growth factor receptor 2 (HER2). "RFS was not significantly different when triple negative breast cancer patients were divided by median ACBD3, but both ER+ and ER− groups had less RFS when tumor ACBD3 was expressed above the median." (PMID 36012147, 2022).
infection (12 papers, 2016 to 2025). The state of being infected such as from the introduction of a foreign agent such as serum, vaccine, antigenic substance or organism. "We followed up on ACBD3 since knocking it out had the greatest effect on LGTV infection, and it affected TBEV and WNV as well." (PMID 40207930, 2025). "Our results suggest that ACBD3 is exploited by flaviviruses to coordinate TERM generation to facilitate successful infection from RNA synthesis to virion assembly." (PMID 40207930, 2025). "Transfection with WT ACBD3 rescued the infection, but transfection with either the GOLD domain on its own or the ACB-Q construct lacking the GOLD domain did not." (PMID 40207930, 2025). "The ectopic expression of 3A or infection with CVB3 drastically alters the intracellular localization of ACBD3." (PMID 35458499, 2022). "The results showed that viral 3A/3AB were exclusively within the membrane fraction; viral 3Dpol, SCAMP3, PI4KIIIβ, and ACBD3 were present in both fractions to various degrees during EV-A71 infection." (PMID 34378951, 2021). "We used western blot analysis to evaluate the expression levels of PI4Kβ and ACBD3 over the course of the infection at several time points in control cells with DMSO and in presence of ITZ at 16 hpi." (PMID 30813555, 2019). "As previously shown, the CVB3 3A protein colocalized with ACBD3 and PI4KB throughout infection in infected HeLawt cells, which implies that both ACBD3 and PI4KB localize to CVB3 ROs." (PMID 30755512, 2019). "Four hours after infection, ACBD3 was found to colocalize with 2B, 2C, and 3A in clusters in the cytoplasm, whereas other Golgi proteins, namely, Giantin, GM130, and TGN46, were not distributed with ACBD3." (PMID 31022988, 2019). "The results indicate that at 4 h post infection, ACBD3 dispersed to cytoplasm and partially localized with 3A." (PMID 28303920, 2017). "ACBD3 was depleted from HeLa cells using one of two different siRNA oligonucleotides prior to infection with wild-type green fluorescent protein (GFP)-expressing S. Typhimurium for 2 h or 9 h." (PMID 27406559, 2016). "Infection by EV causes extensive cellular reorganization, including a protein 3A-mediated generation of replication organelles and the recruitment of cellular proteins such as GBF1, ACBD3, and PI4KB, all supporting viral RNA synthesis and virion assembly." (PMID 35458499, 2022). "As infection continued, a notable fraction of ACBD3 co-localized with 3A." (PMID 28303920, 2017). "Further genetic analysis, together with infection and biochemical assays, showed that SseF, SseG, and ACBD3 form a trimolecular complex and suggested a model in which an interaction between SseF and SseG is required for both effectors to bind ACBD3." (PMID 27406559, 2016). "Therefore, ACBD3 and NS4B work together to promote infection with a mechanism outside of RO generation." (PMID 40207930, 2025). "Based on these observations, it was postulated that during infection, AiV 3A may displace TBC1D22 from ACBD3 to favour binding to PI4KB with a concomitant increased production of PI4P." (PMID 33799649, 2021). "This was confirmed with the use of an infection-free VLP secretion assay, which showed that ACBD3 depletion affects VLP egress independent of any RNA replication effects." (PMID 40207930, 2025).
cancer (7 papers, 2012 to 2025). A tumor composed of atypical neoplastic, often pleomorphic cells that invade other tissues. "By examining the genetic alterations in the ACBD3 gene across human cancers, we observed recurring nonsense mutations (R223*) and frameshift mutations (R190Gfs*), in addition to gains in gene copy numbers." (PMID 40189704, 2025). "The mutational features of ACBD3 in various TCGA cancers were obtained from the cBioPortal database." (PMID 38098097, 2023). "This research was conducted to investigate ACBD3 expression among pan-cancers, investigate the prognostic and diagnostic value of ACBD3 among various tumors, and determine the correlation between ACBD3 mutation characteristics and pan-cancer prognosis." (PMID 38098097, 2023). "These discoveries indicate that ACBD3 has a very important diagnostic and prognostic significance in most cancers, and is expected to be a new biomarker for pan-carcinoma." (PMID 38098097, 2023). "Remarkably, the expression of ACBD3 was actively correlated with cancer-associated fibroblast (CAF) infiltration in HNSC and positively related to neutrophil infiltration in BLCA, COAD, and THCA." (PMID 38098097, 2023). "We also applied the diagnostic value and survival prognosis analysis of ACBD3 in pan-cancers using R language." (PMID 38098097, 2023). "The ROC curve was drawn to explore the diagnostic value of ACBD3 in different cancers, and an AUC value > 0.7 was considered to have a diagnostic value." (PMID 38098097, 2023). "As ACBD3 expression is associated with cancer stem cell formation, it is possible that this staining represents the formation of CSCs or cells that will become them." (PMID 36012147, 2022). "Therefore, ACBD3 gene is either amplified in certain cancer cells to promote tumor growth or mutated in others to enhance metastasis." (PMID 40189704, 2025). "Through interactions with diverse partners, ACBD3 has been implicated in a range of cellular processes, including steroidogenesis, lipid metabolism and transportation, viral replication, Huntington’s disease, and human cancers." (PMID 40189704, 2025). "Given ACBD3’s migration-suppressive role in 1q-diploid cancer cells, such mutations may drive the metastatic dissemination of cancer cells." (PMID 40189704, 2025). "A possible explanation is that other Golgi proteins, such as PAQR11 and PI4K2A, which are highly expressed in mesenchymal cancer cells, may compensate for the changes in Golgi morphology caused by ACBD3 loss." (PMID 40189704, 2025). "According to our pan-cancer analysis of ACBD3, ACBD3 may serve as a novel prognostic and diagnostic biomarker for pan-cancers as it contributes to tumor development." (PMID 38098097, 2023). "In addition, the K-M survival curve for various cancers revealed that ACBD3 was closely associated with the prognosis in PAAD, ACC, SARC, and GBMLGG." (PMID 38098097, 2023). "According to our pan-cancer analysis, ACBD3 may serve as a remarkable prognostic and diagnostic biomarker of pan-cancers as well as contribute to tumor development." (PMID 38098097, 2023). "In summary, we found a statistically significant relationship between ACBD3 expression and immune subtypes, molecular subtypes, diagnosis, prognosis, tumor mutation burden, protein phosphorylation levels, and immune cell infiltration in pan-cancers." (PMID 38098097, 2023). "As direct evidence for the mechanisms that correlate ACBD3 expression and cancer prognosis are very limited, we have used in silico tools to provide a better insight of ACBD3 expression, regulation, and mutational landscape in healthy and cancerous breast tissue." (PMID 36012147, 2022). "The advantage of this study is that we reflected the expression and clinical value of ACBD3 in pan-cancers using a variety of databases in a comprehensive and systematic manner." (PMID 38098097, 2023). "Previous studies demonstrated that ACBD3 was involved in the development and treatment of various types of cancers." (PMID 38098097, 2023).
cancer (continued). "Secondly, this was the first study to analyze the biological significance of ACBD3 in pan-cancers and obtain relatively comprehensive results." (PMID 38098097, 2023). "When compared with normal tissues, ACBD3 expression was statistically upregulated in eleven cancers and downregulated in three cancers." (PMID 38098097, 2023). "ACBD3 expression was remarkably different among various pathological stages of tumors, immune and molecular subtypes of cancers, cancer phosphorylation levels, and immune cell infiltration." (PMID 38098097, 2023). "By exploring the TCGA database, we found that ACBD3 expression was remarkably upregulated in eleven cancers, and downregulated in three cancers." (PMID 38098097, 2023). "Relevant clinical and RNA-sequencing data for normal tissues and 33 tumors from The Cancer Genome Atlas (TCGA) database, the Human Protein Atlas, and other databases were applied to investigate ACBD3 expression in various cancers." (PMID 38098097, 2023). "Previous researches have demonstrated that ACBD3 played a significant role in the development and treatment of different cancers." (PMID 38098097, 2023). "In future studies, we plan to combine various learning methods, such as machine learning, to further understand the function of ACBD3 in various cancers." (PMID 38098097, 2023). "In order to gain a more comprehensive understanding of ACBD3, we are the first to explore its function and expression of ACBD3 in pan-cancers from the perspective of bioinformatic analysis." (PMID 38098097, 2023). "The increased risk of and decreased time to relapse and metastasis support a role for ACBD3 in cancer stem cell formation and maintenance." (PMID 36012147, 2022). "ACBD3 expression was found to be lower in cancer samples compared to adjacent tissue and normal adjacent tissue, which was not expected." (PMID 36012147, 2022). "Samples of human breast tissue from cancer patients were analyzed for ACBD3 expression by immunohistochemical staining." (PMID 36012147, 2022). "Invasive ductal carcinomas were observed to have many invasive cells in the lobules that had low staining for ACBD3, but some cells embedded in them had very high staining." (PMID 36012147, 2022). "However, ACBD3 expression is decreased in the metastatic lesions of several cancer types, including NSCLC, a trend not observed in PI4KB expression levels." (PMID 40189704, 2025). "Genes exhibiting such dichotomy, including TGF-β1, AMPK, and ACBD3, may serve as valuable biomarkers for assessing cancer status and stage." (PMID 40189704, 2025). "Given that ACBD3 interacts with PI4KB, we hypothesize that ACBD3 regulates cancer secretion by modulating the Golgi localization and activity of PI4KB." (PMID 40189704, 2025). "Overexpression of ACBD3 has been identified as a prognostic marker in several human cancers." (PMID 40189704, 2025). "Therefore, we explored the correlation between ACBD3 expression and immune infiltration in different cancers using the TIMER2.0 database." (PMID 38098097, 2023). "The aim of this study was to further explore whether ACBD3 could serve as a new pan-cancer biomarker and to further determine its molecular mechanism and prognostic relevance." (PMID 38098097, 2023). "The high accuracy in diagnosing multiple tumors and its correlation with prognosis indicated that ACBD3 may be a potential biomarker of pan-cancers." (PMID 38098097, 2023). "This comprehensive and systematic pan-cancer analysis of ACBD3 supports further explorations into the critical role of ACBD3 during the development of tumors and offer a comprehensive analytical basis for further molecular, biological, and experimental verification in future clinical decisions." (PMID 38098097, 2023). "The gene alteration characteristics of ACBD3 in TCGA pan-cancer atlas were obtained." (PMID 38098097, 2023). "The human protein atlas was queried to investigate whether high levels of ACBD3 protein were also found in cancers." (PMID 36012147, 2022).
cancer (continued). "High ACBD3 expression has previously been associated with more advanced-stage tumors and with cancer stem cells, so it was unexpected to find no statistical difference between non-metastatic and metastatic breast tissue." (PMID 36012147, 2022). "We hypothesis that ACBD3 levels may rise in normal tissues as part of the tumor development process, rendering high ACBD3 expression a potential marker of early-stage cancer or precancerous breast tissue." (PMID 36012147, 2022). "Further investigations of the role of ACBD3 in cancer stem cell differentiation and tumorigenesis may help increase the understanding of the onset of cancer and develop innovative therapies." (PMID 31022988, 2019). "Homozygous R190G*fs or R223* mutations will eliminate WT ACBD3 proteins, which may not be beneficial for cancer cells." (PMID 40189704, 2025). "Furthermore, CM from ACBD3-deficient cells failed to recruit endothelial and cancer-associated fibroblast cells, a phenotype similar to that observed with PI4KB depletion, suggesting that ACBD3 functions, at least in part, by regulating secretion." (PMID 40189704, 2025). "Although the precise roles of ACBD3 in various cancers remain unclear." (PMID 38098097, 2023). "Thus, we aimed to determine the diverse roles of ACBD3 in pan-cancers." (PMID 38098097, 2023). "No studies have explored the association between ACBD3 and pan-cancer development until now." (PMID 38098097, 2023). "ACBD3 may also provide new directions for cancer treatment targets in the future." (PMID 38098097, 2023). "As such, ACBD3 may also provide new directions for cancer treatment targets in the future." (PMID 38098097, 2023). "Recent studies have demonstrated that ACBD3 is involved in the regulation of PKA activation and ferroptosis, both of which play important roles in cancer progression." (PMID 40189704, 2025). "In human cancer cell lines, PI4KB and ACBD3 are co-expressed." (PMID 40189704, 2025). "The expression levels of ACBD3 are positively correlated with epithelial marker E-Cadherin (CDH1) and negatively correlated with mesenchymal marker Vimentin (VIM) or Zinc Finger E-Box Binding Homeobox 1 (ZEB1) in TCGA LUAD cohort and cancer cell lines." (PMID 40189704, 2025). "In this study, we found that the growth-promoting Golgi protein ACBD3 is amplified and overexpressed in epithelial 1q-LUAD cells but downregulated in migratory mesenchymal cancer cells, further supporting the dichotomous relationship between tumor growth and dissemination." (PMID 40189704, 2025). "It was unexpected to find that ACBD3 scoring was much lower for the cancers compared to either adjacent tissue, as this does not match the findings in cell lines, bioinformatics, or previous publications." (PMID 36012147, 2022). "It is conceivable that IGF1R signaling induces ACBD3 expression, which would increase the pool of available GLUT4-containing vesicles and therefore increase glucose import and energy for the proliferating cancer cells, propagating the Warburg effect." (PMID 36012147, 2022). "Nevertheless, no studies have explored the function of ACBD3 in pan-cancers systematically." (PMID 38098097, 2023).